HIF1A (hypoxia inducible factor 1 subunit alpha)
Diseases named in the same sentence as HIF1A in open-access papers (continued):
Sharing a sentence is not in itself a finding about the gene and the disease.
myocardial infarction (continued). "Conditional knockout of Hif-1α enhances the proliferation of PDGFRα+ cells postcardiac injury, likely driven by priming cell cycle entry after myocardial infarction." (PMID 38788527, 2024). "Previous studies have shown that HIF-1α can help preserve myocardial function and minimize scarring after myocardial infarction, and the toxic effects of some agents have prevented clinical translation so far." (PMID 38994928, 2024). "We recently explored the role of HIF-1α in cardiac fibroblasts (likely FAPs) in response to myocardial infarction." (PMID 38788527, 2024). "HIF‐1α (hypoxia induced factor‐1α), a vital protective signal against hypoxia, has a short lifetime after myocardial infarction (MI)." (PMID 39308185, 2024). "In a myocardial infarct model, CaMK2γ expression decreased due to elevated HIF-1α levels, pointing to its important role in calcium signaling and transcriptional response to hypoxia." (PMID 37175562, 2023). "To summarize, HIF-1a overexpression enhanced the cardiac function in rats, decreased the myocardial infarction area, improved myocardial injury, and diminished the rate of apoptosis in myocardial cells." (PMID 37986153, 2023). "There has also been an investigation into HIF1-α-over-expressing stem cells and their resulting extracellular vesicles, which showed improved neovessel formation and heart function in a rat myocardial infarction model." (PMID 36675188, 2023). "If the HIF-1α content is high, it points to oncological or cardiovascular diseases: hypoxia, strokes, heart attacks, pulmonary hypertension, etc., which disturb, along with concomitant diseases, the self-regulation of HIF-1α and its stabilization." (PMID 36674808, 2023). "In animal models of myocardial infarction by coronary ligation or systemic hypoxia, the accumulation of HIF-1α and HIF-2α persisted for several weeks." (PMID 37175562, 2023). "miR-126 has been shown to protect the heart by promoting angiogenesis and reducing myocardial infarction size by targeting hypoxia inducible factor 1 subunit alpha (HIF-1α)." (PMID 37484982, 2023). "Recently, a murine model of myocardial infarction (MI) was used to examine proinflammatory roles for myeloid HIF-1α and HIF-2α." (PMID 37124241, 2023). "In myocardial infarction mice, HIF-1α up-regulation specifically in cardiomyocytes results in reduced contractility." (PMID 37885997, 2023). "GA was also found to improve heart function in myocardial infarction rats by increasing levels of pro-angiogenic factors, including hypoxia-inducible factor 1-alpha (HIF-1α), VEGF-A, and basic fibroblast growth factor (bFGF)." (PMID 37359709, 2023). "The assay was applied for the detection of HIF-1α-positive exosomes in blood serum samples from model animals with myocardial infarction." (PMID 35884911, 2022). "This suggests that, in response to myocardial infarction and reperfusion, activation of HIF1A coordinates cardioprotective effects by activating the expressions of Netrin-1 and ADORA2B, which both reduce post-ischemic myocardial inflammation." (PMID 36247475, 2022). "Overexpression of HIF-1α in exosomes from mesenchymal stem cells reduced cardiac fibrosis through the promotion of neovessel formation in rats after myocardial infarction." (PMID 35859903, 2022). "Next, serial tissue sections of patients with acute myocardial infarction were immunostained for nuclear HIF-1α, neutrophil elastase and DNA." (PMID 35222361, 2022). "Here we report that in acute myocardial infarction, a condition of pronounced hypoxia, most neutrophils showed high nuclear levels of HIF-1α and displayed a viable nuclear morphology." (PMID 35222361, 2022). "Protein HIF-1α, which controls oxygen transport, represents a potential biomarker of myocardial infarction." (PMID 35884911, 2022).
myocardial infarction (continued). "Given the alteration in the expression of genes involved in cardiac angiogenesis in myocardial infarction, the expression level of Hif-1α and VEGF as two critical genes in angiogenesis was evaluated by qPCR." (PMID 34704139, 2021). "HIF-1α induced regulation of AQP1 has also been linked to edema in peripheral nerve injury in Schwann cells and after myocardial infarction." (PMID 33644043, 2021). "A recent study by Sun and collaborators found that exosomes derived from hypoxia inducible factor 1 α (HIF1α)-overexpressing MSCs resulted in cardioprotection of a rat myocardial infarction model by inducing angiogenesis." (PMID 33918396, 2021). "In this study we identified the novel role of miR-19a-3p in the crosstalk between cardiomyocytes and endothelial cells via paracrine pathway that regulates angiogenesis by targeting HIF-1α in myocardial infarction mice." (PMID 33352533, 2020). "They found that in the cases of human myocardial infarction and of unstable angina pectoris, HIF-1α mRNA expression was strictly confined to the ischemic area, but was not detectable in non-ischemic parts of MI hearts." (PMID 32399898, 2020). "Our findings suggest that a novel mechanism by which bFGF attenuates the injury induced by myocardial infarction by enhancing the accumulation of HIF-1α." (PMID 32848793, 2020). "The present study demonstrated the cardioprotective effect of HIF-1α-overexpressed exosomes on rat myocardial infarction via enhanced angiogenesis and reduced fibrosis." (PMID 32859268, 2020). "The results of the present study indicated that bFGF attenuates myocardial injury by inhibiting apoptosis and promoting angiogenesis via a novel HIF-1α-mediated mechanism and a potential utility of bFGF in protecting against myocardial infarction." (PMID 32848793, 2020). "To further examine the roles of MΦ HIF-1α signaling in the development of replacement fibrosis, we performed myocardial infarction model using mHIF-1α CKO mice." (PMID 31249305, 2019). "•HIF-1α is activated following myocardial infarction, and is a critical transcription factor promoting survival in hypoxia." (PMID 30175272, 2018). "Among these factors, HIF-1α draws our attention since it is a pivotal regulator of the hypoxic response following myocardial infarction." (PMID 25767513, 2015). "Myocardial transfection of HIF-1α combined with MSC transplantation in the peri-infarcted region improved cardiac function four weeks after myocardial infarction." (PMID 24507665, 2014). "We investigated the therapeutic effects of myocardial transfection of HIF-1α and co-transplantation of MSCs on cardiac repair in myocardial infarction by using myocardial transfection of HIF-1α via an adenoviral vector." (PMID 24507665, 2014). "Hypoxia-inducible factor-1α (HIF-1α) is a major regulator of the hypoxic response after myocardial infarction." (PMID 24507665, 2014). "Then the effect of TXL on transcriptional activity of HIF-1α after myocardial infarction was evaluated by EMSA analysis." (PMID 24069057, 2013). "During an acute myocardial infarction, HIF-1α enters into the blood with a subsequent increase in serum level." (PMID 23526997, 2013). "In this study, silybin was shown to alleviate post-myocardial infarction heart failure by downregulating HIF-1α expression and inhibiting its nuclear translocation, which, in turn, reduces the HIF-1α-mediated upregulation of key glycolytic enzymes (PFKFB3, GLUT1, LDHA)." (PMID 40944191, 2025). "Another report has confirmed that MSC-derived Exos overexpressing HIF-1α could promote angiogenesis and thereby mediate cardioprotective effects in patients with myocardial infarction." (PMID 40176111, 2025). "In rodent and porcine models of limb ischemia and myocardial infarction, gene therapy vectors of constitutively active HIF-1α (e.g., AdCA5) and small-molecule PHD inhibitors (e.g., DMOG, Roxadustat) improved capillary density, blood flow, and functional recovery." (PMID 41150799, 2025).
myocardial infarction (continued). "Interestingly, a recent study shows that overexpressing HIF-1α in MSCs leads to exosomes rich in miRNA-221, capable of shrinking infarct size and cardiac fibrotic scarring in a rat myocardial infarction model." (PMID 41303720, 2025). "Furthermore, the observed reduction in HIF-1α expression following GDF15 administration underscores its role in mitigating the hypoxic stress integral to myocardial infarction." (PMID 41023695, 2025). "This work presents an injectable hydrogel using drug itself as crosslinking points, achieving programable release of HIF‐1α stabilizer for treating myocardial infarction (MI), and with which reports the desirable profile of myocardial HIF‐1α expression post MI." (PMID 39308185, 2024). "In addition, HIF-1α-Exos preserved heart function by increasing angiogenesis and reducing fibrosis in a rat myocardial infarction model." (PMID 38790015, 2024). "In conclusion, HIF-1α overexpression in exosomes manifested therapeutic effects on myocardial infarction and could be envisioned as a promising therapeutic method for myocardial infarction." (PMID 32859268, 2020). "The aim of this research is to investigate whether and how the combination of overexpression of hypoxia-inducible factor-1α (HIF-1α) and co-transplantation of mesenchymal stem cells can enhance cardiac repair in myocardial infarction." (PMID 24507665, 2014). "After AS or myocardial infarction (MI), a large number of monocytes are recruited to the damaged area, a process that supports their energy demands through HIF-1α-driven glycolysis." (PMID 40513070, 2025). "Sirt1 effectively reduces cardiomyocyte apoptosis and myocardial infarction size while enhancing cardiac function post-MI, primarily through the Phd3/Hif-1α signaling pathway." (PMID 40087582, 2025). "A significant reduction in Sirt1 and Phd3 expression, along with an increase in Hif-1α and cleaved caspase-3, was observed in a time-dependent manner post-myocardial infarction (MI)." (PMID 40087582, 2025). "In the context of myocardial infarction (MI), PHIs hold promise as a reparative strategy to attenuate adverse remodeling by increasing HIF-1α levels." (PMID 38994928, 2024). "Moreover, several beneficial effects of Dan Shen in HF prevention include an anti-cardiac hypertrophic effect, reducing adriamycin-induced cardiomyopathy, and improving cardiac angiogenesis and ejection function by modulating the HIF1α/VEGFA signaling pathway after myocardial infarction." (PMID 35898268, 2022). "Indeed, HIF-1α has previously been found to increase SgII production in skeletal muscle subjected to hypoxia, and we found SgII production increased in the LV of animals with myocardial infarction and HF." (PMID 22655045, 2012). "In addition, Zhao and colleagues suggested recently that HIF-1α is also involved in ischemic postconditioning, and pharmacological augmentation of HIF-1α expression may even enhance the myocardial infarct-sparing effect." (PMID 22011328, 2011). "Collectively, these findings suggested that GPX3 mediates Hif1α expression through LSD1, thereby enhancing cardiomyocyte survival and facilitating cardiac repair post‐myocardial infarction." (PMID 39900557, 2025). "In a pig model of myocardial infarction, NXK improves macrophage function by modulating the HIF-1α/PDK1 axis, promoting the conversion of macrophages to the M2 phenotype, and thus accelerating cardiac repair." (PMID 41583440, 2025). "This study extends previous findings indicating that upregulation of P2X7R during myocardial infarction activates the Nox4/PERK/ATF4 pathway, which is known to regulate HIF-1α and VEGF." (PMID 41295364, 2025). "Consistently, following acute myocardial infarction (AMI), we observed a marked decrease in Sirt1 expression, accompanied by an increase in Hif-1α and the cleaved caspase-3/caspase-3 ratio within the infarcted myocardial regions." (PMID 40087582, 2025).
myocardial infarction (continued). "Therefore, hChAT tg hearts were more resilient to hypoxia, ischemia, or myocardial infarction (MI) due to enhanced protein expression levels of hypoxia-inducible factor (HIF)-1α, even under normoxic conditions." (PMID 38601043, 2024). "Overexpression of miR-210 in mice model of myocardial infarction (MI) promotes peri-infarct revascularization, with a significant upregulation of VEGF expression and a mild increase in HIF-1α expression." (PMID 39552721, 2024). "Studies indicate that Tongxinluo can increase VEGF expression and HIF-1α expression activity by enhancing the phosphorylation of ERK and AKT, thereby increasing angiogenesis and improving cardiac function after myocardial infarction." (PMID 37427386, 2023). "In a mouse model for myocardial infarction (MI), it was demonstrated that ischemic conditions increased FABP3 expression under the regulation of hypoxia-inducible factor (HIF)-1α." (PMID 37207357, 2023). "It was found that the protein expressions of HIF-1α, VEGFs, and COX-2 were increased with the marked increases of Nur77 and p-PI3K protein expressions in the heart of myocardial infarction mice." (PMID 37204425, 2023). "Electroacupuncture pretreatment promoted angiogenesis by increasing serum HIF-1α and VEGF protein expression in myocardial infarction area." (PMID 35578250, 2022). "It was reported increased HIF-1α and VEGF expression in ADSCs significantly promoted angiogenesis and functional recovery in the myocardial infarction in animal models." (PMID 34307320, 2021). "For example, ischemic preconditioning provided strong cardioprotection against ischemia through the stabilization of cardiac HIF-1α, and treatment with the HIF-1α activator dimethyloxaloylglycine (DMOG) attenuated myocardial infarction." (PMID 34205318, 2021). "The results showed that SPC significantly elevated the protein expression levels of HIF-1α, VEGF, and eNOS, and the myocardial infarction area and ROS were therefore decreased." (PMID 28659817, 2017). "In a murine myocardial infarction model, TXL enhanced angiogenesis in the ischemic myocardium by up-regulating HIF-1α and VEGF expression, thereby improving ischemic myocardial function." (PMID 26908443, 2016). "Therefore, the HIF-1α gene could be worth consideration as a target in the prosurvival approaches for MSC therapies, since beneficial results were seen in HIF-1α-engineered MSCs in trials with a mouse hind-limb ischemia model and in a rat myocardial infarction model." (PMID 27242906, 2016). "Our results demonstrate that intramyocardial injection of Ad-HIF-1α combined with MSC transplantation was potent to promote angiogenesis, and led to improved cardiac performance after myocardial infarction in the rats." (PMID 24507665, 2014). "Accordingly, we plan to test the hypothesis that exogeneous expression of HIF-1α in the ischemic area may increase the local survival and engraftment of the transplanted MSCs, enhance the angiogenesis, and improve cardiac performance in rats after myocardial infarction." (PMID 24507665, 2014). "In addition, a published report demonstrated that PKM2 interacts with hypoxia-inducible factor 1-alpha (HIF-1α), facilitating the isoform shift from PKM1 to PKM2 under myocardial infarction (MI) conditions." (PMID 41148838, 2025). "In addition, exercise training upregulates the levelof hypoxia-Inducible factor 1-alpha (HIF-1α), triggering angiogenesispromotion through the PI3K-Akt-eNOS and MAPK signaling pathway and protectscardiac function after myocardial infarction." (PMID 39076229, 2022). "We suggest that the role of LRP5 as a regulator of HIF-1α stability under hypoxic conditions can be exploited as a novel therapeutic strategy targeting LRP5 for the treatment of myocardial infarction." (PMID 34205318, 2021). "Inhibiting miR-155 could reduce myocardial infarct size, suppress I/R-induced cardiomyocyte apoptosis, and maintain the MMP to alleviate I/R-induced injury via specific regulation of HIF-1α." (PMID 31807249, 2019).
myocardial infarction (continued). "However, several authors suggested a HIF1-α induced upregulation of ADAMTS1 under hypoxia in endothelial cells and an early expression after myocardial infarction." (PMID 31036020, 2019). "Similarly, transgenic mice having HIF-1α overexpression had diminished infarct size, increased capillary density and enhanced VEGF and iNOS expression following myocardial infarction." (PMID 22043202, 2010). "The association of platelet endothelial cell adhesion molecule 1 (PECAM1), hypoxia-inducible factor 1 subunit alpha (HIF1A), and KIAA1462 in myocardial infarction (MI) was investigated." (PMID 30678728, 2019). "In these studies, in spite of HIF1A being not a key target, it was displayed in the core PPI network, which highlighted its important role in treatment of atherosclerosis or acute myocardial infarction." (PMID 40478326, 2025).